HK3 (hexokinase 3)
Diseases named in the same sentence as HK3 in open-access papers (continued):
Sharing a sentence is not in itself a finding about the gene and the disease.
glioma (3 papers, 2017 to 2024). A benign or malignant brain and spinal cord tumor that arises from glial cells (astrocytes, oligodendrocytes, ependymal cells). "In our work, we analyzed the co-expression relationship between glycolysis related genes and immune checkpoint genes based on data from TCGA and CGGA and found an association between the expression level of HK3 and glioma immune status." (PMID 37779195, 2023). "Consequently, we investigated the association between HK3 expression and immune cell infiltration in glioma." (PMID 37779195, 2023). "Taken together, these data showed that Hk3 expression might be closely associated with the reprogramming of the immunosuppressive microenvironment in glioma." (PMID 37779195, 2023). "Overall, these results indicated that high HK3 expression was associated with poor prognosis in patients with glioma and that the gene expression level could independently predict OS." (PMID 37779195, 2023). "Based on the TCGA datasets, the mesenchymal subtype, which was recognized as a more aggressive subtype of glioma, showed the higher expression of HK3 compared with other GBM subtypes." (PMID 37779195, 2023). "In this study, through GO analysis of the biological role of HK3, we found that HK3 played a pivotal role in inflammatory activities and immunological reactions in glioma." (PMID 37779195, 2023). "The advantage of our research was that we first assessed the prognostic role of the differential expression levels of HK3 in glioma." (PMID 37779195, 2023). "We also systematically analyzed HK3 expression levels in various grades and subtypes of glioma, its latent biological effect, and its prognostic value." (PMID 37779195, 2023). "All these results indicated that a high level of HK3 expression was involved in the malignant progression of glioma." (PMID 37779195, 2023). "The present work mainly concentrated on the biological role of HK3 in glioma and offered a novel insight of HK3 regulating the activation of immune cells in the glioma microenvironment." (PMID 37779195, 2023). "In glioma, HK3 enhances immune cell infiltration and malignancy." (PMID 38714539, 2024). "Therefore, high expression of HK3 had a positive correlation with the infiltration of immune cells and predicts shorter overall survival (OS) in glioma patients." (PMID 37779195, 2023). "We investigated the prognostic value of HK3 expression in glioma." (PMID 37779195, 2023). "Our study showed that HK3 significantly stimulated immune cell infiltration into the glioma TME." (PMID 37779195, 2023). "Benefiting from these positive studies, we assume that HK3 may also have an effect on infiltration level of immune cells in glioma TME." (PMID 37779195, 2023). "In this study, the results of the in vivo experiments demonstrated that the overexpression of Hk3 could promote the malignant progression of glioma in mice along with increased infiltration level of M2 macrophages, neutrophils, and various subtypes of activated memory CD4+ T cells." (PMID 37779195, 2023). "In our work, we analyzed the co-expression relationship between glycolytic genes and immune checkpoints based on the transcriptomic data from The Cancer Genome Atlas (TCGA) and Chinese Glioma Genome Atlas (CGGA) and found the correlation between HK3 expression and glioma tumor immune status." (PMID 37779195, 2023). "The glioma was subsequently divided into mesenchymal and non-mesenchymal subtypes for ROC curve analysis, and the results demonstrated that HK3 expression was a good predictor of mesenchymal subtype." (PMID 37779195, 2023). "The results demonstrated that HK3 could induce higher infiltration level of M2 macrophages, neutrophils, and various subtypes of activated memory CD4+ T cells into the TME and could be a predictor of the unfavorable prognosis of glioma in vitro and in vivo." (PMID 37779195, 2023).
glioma (continued). "In summary, our current work demonstrated that HK3 could increase the infiltration of M2 macrophages, neutrophils, and various subtypes of activated memory CD4+ T cells into the tumor microenvironment and could be a predictor of the unfavorable prognosis of glioma." (PMID 37779195, 2023). "Therefore, although HK3 was a glycolysis enzyme, we hypothesized that HK3 might not play a major role in glycolysis in glioma." (PMID 37779195, 2023). "The rate-limiting, irreversible and glycolysis-related enzymes hexokinase (HK2 and HK3) and pyruvate kinase (PKM2), but not HK1 or the pyruvate kinase isoform PKLR, were also expressed at lower levels in IDH1MUT glioma compared with IDH1WT glioma." (PMID 28467784, 2017).
neuroblastoma (3 papers, 2024 to 2025). Neuroblastoma (NB) is the most common solid, extracranial childhood tumor. "M2-like macrophages are highly infiltrated in neuroblastoma tumors and are strongly associated with HK3, as confirmed in bioinformatic analysis and immunohistochemistry or Western blotting of clinical tissues." (PMID 38714539, 2024). "Using the CCK8 assay, it was observed that M2-TAMs with low HK3 expression cause a decrease in the proliferation of two neuroblastoma cell lines." (PMID 38714539, 2024). "This suggests a significant regulatory role of HK3 in neuroblastoma tumorigenic capacity when co-cultured with tumor-associated macrophages, particularly those exhibiting an M2-like phenotype." (PMID 38714539, 2024). "In neuroblastoma (NB), hexokinase-3 (HK3), a key enzyme in glucose metabolism, is correlated with M2 macrophage infiltration, increased lactate secretion by tumor cells, and histone lactylation." (PMID 40584966, 2025). "The dual role of HK3 in coordinating neuroblastoma malignancy underscores its potential as a multifaceted target for tumor therapy and diagnosis." (PMID 38714539, 2024). "Next, the effect of HK3 knockdown on the malignant biological behavior phenotype of neuroblastoma was investigated in vitro." (PMID 38714539, 2024). "Subsequent verification demonstrated that HK3 activation in neuroblastoma triggers the PI3K-AKT signal transduction pathway, thereby influencing the expression of CXCL14 in neuroblastoma." (PMID 38714539, 2024). "Next, a subcutaneous xenograft tumor model was used to identify the effect of HK3 knockdown on the malignant biological phenotype of neuroblastoma in vivo." (PMID 38714539, 2024). "This suggests that CXCL14 serves as a downstream molecule in neuroblastoma (NB), and HK3 regulates the recruitment and polarization of M2-like macrophages through CXCL14." (PMID 38714539, 2024). "Collectively, these findings underscore the pivotal role of HK3 in orchestrating M2-like macrophage recruitment and polarization within the context of neuroblastoma." (PMID 38714539, 2024). "In our study, it was initially observed that overexpression of HK3 correlated with a poor prognosis in neuroblastoma, with HK3 expression consistently heightened in NB INSS IV." (PMID 38714539, 2024). "Taken together, these findings support the notion that inhibiting HK3 in neuroblastoma, while simultaneously suppressing its interaction with macrophages, can effectively mitigate tumor tumorigenesis and progression." (PMID 38714539, 2024). "It establishes HK3 as a promising dual-functional biomarker and therapeutic target in combating neuroblastoma." (PMID 38714539, 2024). "In preliminary experiments, it was identified that HK3 in neuroblastoma regulates the polarization and recruitment of M2-like macrophages through the secretion of CXCL14." (PMID 38714539, 2024). "Subsequently, the impact of HK3 in M2-like macrophages on the biological behavior of neuroblastoma in vitro was explored." (PMID 38714539, 2024). "Together, HK3-regulated the progression of neuroblastoma through the PI3K-Akt signaling pathway, and BKM120 effectively inhibited the activation of the PI3K/Akt pathway." (PMID 38714539, 2024). "Knockdown of HK3 in M2 macrophages was observed to diminish the proliferation, invasion, and migration capabilities of neuroblastoma cells." (PMID 38714539, 2024). "In this experiment, transcriptome sequencing and GSEA enrichment analysis were performed on SK-N-SH neuroblastoma cells with knocked-down HK3 and the control group." (PMID 38714539, 2024). "It was observed that the recruitment and polarization abilities of M2 macrophages were diminished following co-culture with HK3-knockdown neuroblastoma cells." (PMID 38714539, 2024). "Transcriptome sequencing and GSEA enrichment analysis revealed a significant reduction in CXCL14 expression in neuroblastoma cells with knocked-down HK3, accompanied by a notable decrease in secreted CXCL14." (PMID 38714539, 2024).
neuroblastoma (continued). "Therefore, HK3 exerts its influence on the interaction between neuroblastoma cells and M2-like macrophages by modulating CXCL14 via the PI3K-AKT signaling pathway." (PMID 38714539, 2024). "Consequently, HK3 modulates the interaction between neuroblastoma and M2-like macrophages by secreting CXCL14 through the PI3K/AKT signaling pathway." (PMID 38714539, 2024). "However, the precise role of HK3 in neuroblastoma progression and its interactions within the tumor microenvironment remains to be fully understood." (PMID 38714539, 2024). "In summary, our study results indicate that HK3 serves as a regulatory factor in the NB-TAM interaction, modulating the crosstalk between neuroblastoma cells and M2-like macrophages." (PMID 38714539, 2024). "Consequently, it is believed that M2-like macrophages with high expression of HK3 can regulate the malignant biological behavior of neuroblastoma, and they also hold potential as therapeutic targets for NB." (PMID 38714539, 2024). "Therefore, HK3 not only directly regulates the malignant biological behaviors of tumor cells, such as proliferation, migration, and invasion, but also recruits and polarizes M2-like macrophages through the PI3K/AKT-CXCL14 axis in neuroblastoma." (PMID 38714539, 2024). "Elucidating the significant role of HK3 in the pathogenesis of neuroblastoma not only deepens our understanding of the dynamics of the TME but also paves the way for new intervention strategies, ultimately improving clinical management and prognosis for neuroblastoma patients." (PMID 38714539, 2024).
viral infections (3 papers, 2022 to 2025). "Among the 6 genes, over-expressed genes (HK3, DEFA4, BATF) were positively correlated with severity of viral infection, and under-expressed genes (HLA-DPB1, LY86, TGFBI) were negatively correlated with severity." (PMID 35042868, 2022). "Each of the 6 genes were significantly differentially expressed between patients with viral infections who survived and those who did not, of which 3 genes (DEFA4, BATF, HK3) were higher and 3 genes (TGFBI, LY86, HLA-DPB1) were lower in those who died." (PMID 35042868, 2022).
diabetes (2 papers, 2018 to 2021). "HK3, FCN1,CAMK1, GLUT1/SLC2A1 and GLUT3/SLC2A3 are involved in glucose and insulin metabolism that played vital role in development of obesity and diabetes." (PMID 29876008, 2018).
fatty liver disease (2 papers, 2023 to 2025). A reversible condition wherein large vacuoles of triglyceride fat accumulate in liver cells via the process of steatosis. "The interactions between saroglitazar and ferulic acid with different enzymes and metabolites involved in metabolic dysfunction-associated fatty liver disease (MASLD), such as SORD, HK1, HK2, MgATP, KHK, HK3, ALDOB, ALDOC, and fructose-1-phosphate (F1P)." (PMID 40130107, 2025).
hepatocellular carcinoma (2 papers, 2010 to 2023). A malignant tumor that arises from hepatocytes. "Mammalian cells possess four HK isoforms (HK1, HK2, HK3, and HK4) although HK2 is the predominant enzyme expressed by cancer cells including hepatocellular carcinoma (HCC)." (PMID 37059726, 2023).
lung carcinoma (2 papers, 2020 to 2021). "The analysis of the TCGA database with TIMER showed that HK3 is significantly downregulated in lung cancer tissues, while HK1 and HK2 are significantly upregulated at the same time." (PMID 32508023, 2020). "In lung cancer patients’ tissues, it could be detected distinctly that when HK3 was losing, the PD‐L1 levels were increased." (PMID 32508023, 2020). "So, we speculated that HK3, as an enzyme, does not play a major role in glycolysis in lung cancer cells." (PMID 32508023, 2020).
renal cell carcinoma (2 papers, 2021 to 2025). "Among HK isoenzymes, HK3 is highly expressed in renal cell carcinoma (RCC) tissues." (PMID 39987091, 2025). "At present, there are few reports on HK3 in renal cell carcinoma." (PMID 33564363, 2021).
amenorrhea (1 paper, 2020). The absence of menses in a woman who has achieved reproductive age. "We also identified a second combination of POU5F1 (c.87G>T;p.Trp29Cys) and HK3 (c.2026C>T;p.Pro676Ser) in POI-15 presenting with secondary amenorrhea." (PMID 33095795, 2020).
autoimmune disease (1 paper, 2022). A disorder resulting from loss of function or tissue destruction of an organ or multiple organs, arising from humoral or cellular immune responses of the individual to their own tissue constituents. "We used RRA analysis to evaluate the expressions of 402 key metabolic genes in these patients with autoimmune diseases, and found that HK3 was the most significant key metabolic gene with abnormal expression in autoimmune diseases (adjusted P=1.2×10-9)." (PMID 36325332, 2022). "The targeted regulation of HK3 to control macrophage polarization is expected to be a new approach to effective treatment of autoimmune diseases such as AITD." (PMID 36325332, 2022). "Robust rank aggregation (RRA) method revealed that hexokinase 3 (HK3) was the most aberrantly expressed metabolic gene in autoimmune diseases." (PMID 36325332, 2022).
central precocious puberty (1 paper, 2021). "Our data only identified HK3 without HK1, 2, 4 that suggested HK3 may also play a particular role in central precocious puberty and further explore the distribution of HK3 in central precocious puberty patients’ tissue would be important to clarify its functions." (PMID 34748517, 2021).
colon adenocarcinoma (1 paper, 2020). "Besides, HK3 is associated with a CpG island methylated phenotype (CIMP) in colon adenocarcinoma (COAD)." (PMID 33024640, 2020).
kidney cancer (1 paper, 2022). Primary or metastatic malignant neoplasm involving the kidney. "High expression of HK3 was associated with poor OS in kidney cancer." (PMID 36712881, 2022).
nasal polyp (1 paper, 2021). "Next, we identified the protein level of the seven hub genes (ALOX5AP, BCL2A1, BTK, CYBB, NCF2, HCK, and HK3) from nasal polyps from CRSwNPs and nasal mucosa from healthy controls." (PMID 33603773, 2021). "We found that ALOX5AP, BCL2A1, BTK, CYBB, NCF2, HCK, and HK3 were broadly expressed on both epithelial layer and stromal layer in nasal polyp tissues." (PMID 33603773, 2021). "Our study has proved the increased expression of ALOX5AP, BCL2A1, BTK, CYBB, NCF2, HCK, and HK3 by mRNA and protein levels in nasal polyps." (PMID 33603773, 2021). "The western blot results showed the expression level of ALOX5AP, BTK, CYBB, NCF2, HCK, and HK3 in CRSwNP was significantly increased in nasal polyps compared to control subjects." (PMID 33603773, 2021). "Moreover, the immunohistochemistry stain results also demonstrated that the protein level of ALOX5AP, BCL2A1, BTK, CYBB, NCF2, HCK, and HK3 were significantly increased in nasal polyps compared to control subjects." (PMID 33603773, 2021).
rheumatoid arthritis (1 paper, 2025). A chronic, systemic autoimmune disorder characterized by inflammation in the synovial membranes and articular surfaces. "HK3 was identified as a key protein that is highly expressed in rheumatoid arthritis (RA) synovial fluid." (PMID 41300284, 2025).
schizophrenia (1 paper, 2018). A major psychotic disorder characterized by abnormalities in the perception or expression of reality. "This variation could have biological relevance when both HK2 and HK3 elements are expressed, such as in ALS and schizophrenia." (PMID 30072963, 2018).
thyroiditis (1 paper, 2022). Inflammation of the thyroid gland. "In other words, M1 and M2 were significantly polarized in the wild-type thyroiditis group compared with the HK3- knockout thyroiditis group." (PMID 36325332, 2022).